NIT1 (nitrilase 1)
Description:
Catalyzes the hydrolysis of the amide bond in N-(4-oxoglutarate)-L-cysteinylglycine (deaminated glutathione), a metabolite repair reaction to dispose of the harmful deaminated glutathione. Plays a role in cell growth and apoptosis: loss of expression promotes cell growth, resistance to DNA damage stress and increased incidence to NMBA-induced tumors. Has tumor suppressor properties that enhances the apoptotic responsiveness in cancer cells; this effect is additive to the tumor suppressor activity of FHIT. It is also a negative regulator of primary T-cells.
Synonyms: BSVD4
Tractability: PROTAC: ubiquitination databases record sites on it; its protein half-life has been measured.
Target class: Enzyme; Hydrolase
Gene: Protein-coding gene on chromosome 1 (161,118,082 to 161,125,445, forward strand). Ensembl gene ENSG00000158793.
Subcellular location: Mitochondrion (Isoform 2); Cytoplasm (Isoform 1)
Subcellular location (Human Protein Atlas): Cytosol; Mitochondria
Gene Ontology:
Molecular function: deaminated glutathione amidase activity; hydrolase activity, acting on carbon-nitrogen (but not peptide) bonds, in linear amides
Biological process: glutathione metabolic process
Cellular component: mitochondrion; nucleus; cytoplasm
Genetic constraint (gnomAD): Loss-of-function variants: 30 observed, 38.97 expected, observed/expected ratio (o/e) 0.77, 90% interval 0.57 to 1.04. The upper end of that interval is the gene's LOEUF score, 1.04, which puts it in group 4 of 6, group 1 being the genes least tolerant of losing a copy. Missense variants: 438 observed, 432.94 expected, observed/expected ratio (o/e) 1.01, 90% interval 0.94 to 1.1. Synonymous variants: 151 observed, 165.17 expected, observed/expected ratio (o/e) 0.91, 90% interval 0.8 to 1.05.
Homologues: Orthologues: chimpanzee NIT1 (98% identical), macaque NIT1 (97% identical), dog NIT1 (94% identical), rabbit NIT1 (93% identical), pig NIT1 (92% identical), rat Nit1 (86% identical), mouse Nit1 (84% identical), guinea pig NIT1 (83% identical), tropical clawed frog nit1 (53% identical), zebrafish nit1 (51% identical), Drosophila melanogaster NitFhit (45% identical), Caenorhabditis elegans nft-1 (43% identical). Paralogues in human: NIT2 (32% identical), UPB1 (24% identical).